NUP50 (nucleoporin 50)
Description:
Component of the nuclear pore complex that has a direct role in nuclear protein import. Actively displaces NLSs from importin-alpha, and facilitates disassembly of the importin-alpha:beta-cargo complex and importin recycling. Interacts with regulatory proteins of cell cycle progression including CDKN1B (By similarity). This interaction is required for correct intracellular transport and degradation of CDKN1B (By similarity).
Synonyms: NPAP60L; NPAP60
Tractability: Small molecule: a structure with a bound ligand is known. Antibody: UniProt places it where antibodies can reach, with medium confidence. PROTAC: UniProt records ubiquitination sites on it; ubiquitination databases record sites on it; its protein half-life has been measured.
Gene: Protein-coding gene on chromosome 22 (45,163,925 to 45,188,017, forward strand). Ensembl gene ENSG00000093000.
Subcellular location: Nucleus, nuclear pore complex; Nucleus membrane
Subcellular location (Human Protein Atlas): Nuclear membrane; Nucleoplasm
Pathways (Reactome):
Disease: Defective TPR may confer susceptibility towards thyroid papillary carcinoma (TPC); HCMV Early Events; HCMV Late Events; NEP/NS2 Interacts with the Cellular Export Machinery; NS1 Mediated Effects on Host Pathways; Nuclear import of Rev protein; Rev-mediated nuclear export of HIV RNA; SARS-CoV-2 activates/modulates innate and adaptive immune responses; Transport of Ribonucleoproteins into the Host Nucleus; Viral Messenger RNA Synthesis; Vpr-mediated nuclear import of PICs
Metabolism of RNA: Transport of Mature mRNA Derived from an Intronless Transcript; Transport of Mature mRNA derived from an Intron-Containing Transcript; Transport of the SLBP Dependant Mature mRNA; Transport of the SLBP independent Mature mRNA; snRNP Assembly; tRNA processing in the nucleus
Metabolism of proteins: SUMOylation of DNA damage response and repair proteins; SUMOylation of DNA replication proteins; SUMOylation of RNA binding proteins; SUMOylation of SUMOylation proteins; SUMOylation of chromatin organization proteins; SUMOylation of ubiquitinylation proteins
Metabolism: IP3 and IP4 transport between cytosol and nucleus; IP6 and IP7 transport between cytosol and nucleus; IPs transport between nucleus and cytosol; Regulation of Glucokinase by Glucokinase Regulatory Protein
Cell Cycle: Nuclear Pore Complex (NPC) Disassembly
Cellular responses to stimuli: Regulation of HSF1-mediated heat shock response
Immune System: ISG15 antiviral mechanism
Gene Ontology:
Molecular function: protein binding
Biological process: nucleocytoplasmic transport; protein import into nucleus
Cellular component: nuclear envelope; nuclear membrane; nucleoplasm; nuclear pore
Genetic constraint (gnomAD): Loss-of-function variants: 11 observed, 27.47 expected, observed/expected ratio (o/e) 0.4, 90% interval 0.25 to 0.66. The upper end of that interval is the gene's LOEUF score, 0.66, which puts it in group 2 of 6, group 1 being the genes least tolerant of losing a copy. Missense variants: 379 observed, 469.51 expected, observed/expected ratio (o/e) 0.81, 90% interval 0.74 to 0.88. Synonymous variants: 167 observed, 176.61 expected, observed/expected ratio (o/e) 0.95, 90% interval 0.83 to 1.08.
Gene-disease validity (ClinGen):
ClinGen rates the evidence that NUP50 causes each of these diseases.
amyotrophic lateral sclerosis (autosomal dominant): Limited. Amyotrophic lateral sclerosis (ALS) is a neurodegenerative disease characterized by progressive muscular paralysis reflecting degeneration of motor neurons in the primary motor cortex, corticospinal tracts, brainstem and spinal cord.
Homologues: Orthologues: chimpanzee NUP50 (99% identical), macaque NUP50 (97% identical), dog NUP50 (82% identical), rat Nup50 (79% identical), pig NUP50 (78% identical), mouse Nup50 (78% identical), rabbit NUP50 (76% identical), guinea pig NUP50 (70% identical), rat Nup50-ps1 (54% identical), mouse Nup50l (54% identical), zebrafish nup50 (49% identical), tropical clawed frog nup50 (49% identical), and 2 more.
Diseases named in the same sentence as NUP50 in open-access papers:
NUP50 is named in the same sentence as 15 diseases in open-access papers, as found by Europe PMC text mining. Sharing a sentence is not in itself a finding about the gene and the disease. The quoted sentences say what the papers report.
cognitive deficits (1 paper, 2025). "Additional genes from Regions 2 and 3 (PHF21B, SULT4A1, SCUBE1, and NUP50) we speculate that they may further contribute to cognitive deficits, neurodevelopmental features, and growth abnormalities." (PMID 40429797, 2025).
HIV-1 infection (1 paper, 2022). The type species of lentivirus and the etiologic agent of acquired immunodeficiency syndrome (AIDS). "On the other hand, HIV-1 infection can be inhibited via a mechanism that involves targeted repression of NUP50." (PMID 35632621, 2022).
motor neuron disease (1 paper, 2023). "Thus, the loss of function of NUP50 is toxic to motor neurons, and sufficient to lead to motor neuron disease." (PMID 36670122, 2023).
sarcoma (1 paper, 2020). A usually aggressive malignant neoplasm of the soft tissue or bone. "In summary, here we demonstrate that ISG15, NUP50, PTTG1, SERPINE1, and TSR1 are highly expressed in sarcoma tissues and associated with sarcoma metastasis and poor prognosis." (PMID 33123466, 2020). "The results of qRT-PCR suggested that ISG15, NUP50, PTTG1, SERPINE1, and TSR1 were highly expressed in sarcoma tissues." (PMID 33123466, 2020). "The results of immunohistochemistry indicated that SG15, NUP50, PTTG1, SERPINE1, and TSR1 were highly expressed in sarcoma tissues." (PMID 33123466, 2020). "To validate whether ISG15, NUP50, PTTG1, SERPINE1, and TSR1 are differentially expressed in sarcoma tissues, we experimentally validated their expression in the tissues of 10 sarcoma patients." (PMID 33123466, 2020). "Taken together, results of these experiments suggest that high expression levels of ISG15, NUP50, PTTG1, SERPINE1, and TSR1 exert a positive regulatory effect on metastasis, suggesting poor prognosis, and that Tanespimycin may effectively treat LMS sarcoma subtype." (PMID 33123466, 2020).
viral infections (1 paper, 2021).
cancer (2 papers, 2025). A tumor composed of atypical neoplastic, often pleomorphic cells that invade other tissues. "Hits that scored as selective dependencies in the dual ARID1 paralog-deficient setting included POLA2, RAPTOR, and NUP50, corresponding to pathways such as MYC targets, G2/M checkpoint, DNA replication and undifferentiated cancer signatures." (PMID 41279405, 2025). "We observed that TMEM160 is localized in the nucleus and cytoplasm and dynamic localization during mitosis of cancer cells and discovered a novel interaction between TMEM160 and nuclear proteins such as NUP50." (PMID 39940865, 2025).
genetic disease (1 paper, 2019). "Further variable members of the NPC were found to be ALADIN (AAAS) (p = 0.12, one-sided t test), which potentially binds to transmembrane nucleoporins and has been linked to genetic disease, as well as NUP50 (FDR-corrected p = 0.022, one-sided t test), a subunit involved in active nuclear import." (PMID 31031010, 2019).
tumor (1 paper, 2026). "In contrast, supplementation with NUP50-MUT effectively blocked the tumor-promoting effects of GALNT7 overexpression." (PMID 42173248, 2026). "In vivo, using nude mouse xenograft and lung metastasis models, we confirmed that GALNT7 overexpression can synergize with NUP50-WT to significantly promote tumor growth and metastasis, while also enhancing the levels of NUP50 and VVA." (PMID 42173248, 2026).
NUP50 also shares sentences with these, for which no sentence is quoted: autoimmune disease (1 paper); colorectal adenocarcinoma (1); dengue (1); glioblastoma (1); lung adenocarcinoma (1); multiple myeloma (1); neurodevelopmental disorder (1).